BRAF (B-Raf proto-oncogene, serine/threonine kinase)
Diseases named in the same sentence as BRAF in open-access papers (continued):
Sharing a sentence is not in itself a finding about the gene and the disease.
melanoma (continued). "We present the novel finding that down-regulation of CDK11 protein expression reduced cell survival and disrupted cell cycle function in both BRAF- and NRAS-mutant melanomas." (PMID 30987032, 2019). "When combined with BRAF inhibitor, PLX4032, in similar melanoma mouse models, PLX-3397 was shown to substantially reduce M2 phenotype macrophage recruitment, leading to significant tumor growth suppression." (PMID 31439034, 2019). "We determined steady state mRNA expression levels for both CDK11 genes in cultured cells, comparing several BRAF- and NRAS-mutant melanoma cell lines and using adult primary human epidermal melanocytes as a reference control." (PMID 30987032, 2019). "In addition, blocking the BRAF-MAPK signaling pathway in BRAF signaling-addicted melanoma cells in vitro triggered the recognition of tumor cell antigens by tumor-infiltrated T lymphocytes; BRAF blockade and adoptive T cell therapy may confer synergistic effects." (PMID 31775797, 2019). "Several of these have proven successful in the clinic, including the MEK1/2 inhibitors (MEKi) trametinib and cobimetinib, and the BRAF inhibitors (BRAFi) vemurafenib and dabrafenib, all of which are approved for the treatment of BRAFV600E/K-mutant melanoma." (PMID 35582726, 2019). "NRAS and BRAF both play a part in the mitogen-activated protein kinase (MAPK) pathway, which significantly contributes to melanoma development." (PMID 31398831, 2019). "Pharmacological co-targeting of NFATc2 and EZH2 exerted significant anti-tumor effects in distinct melanoma subsets, including BRAF-mutant but BRAF-inhibitor-resistant cell lines, as well as NRAS mutant and BRAF/NRAS wild-type tumors." (PMID 30710146, 2019). "In conclusion, we have uncovered a range of proliferative responses to dual BRAF* and NRAS* expression in melanoma lines." (PMID 30651601, 2019). "While we also observed a high recall for BRAF, NF1, and TWT drug combination predictions, we found a lower recall (0.29) specifically for the IPC-298 NRAS-mutant melanoma cell line." (PMID 30820351, 2019). "Small molecule inhibitors of BRAF and MEK have proven effective at inhibiting tumor growth in melanoma patients, however this efficacy is limited due to the almost universal development of drug resistance." (PMID 31350469, 2019). "In particular, we focused on KIT, BRAF, and BCL-2, three relevant target genes in melanoma known to bear G4-forming sequences within their promoters." (PMID 31635389, 2019). "Potential BRAF inter-tumor heterogeneity is clinically important because of the risk of treating patients with unnecessary targeted therapies (loss of mutation in metastasis) or disturbing beneficial targeted therapies from patients (mutations in metastasis but not in primary melanoma)." (PMID 31817947, 2019). "By acutely down-regulating CDK11 protein expression via siRNA transfection, both BRAF- and NRAS-mutant melanoma cells showed significantly reduced cell survival and disrupted cell cycle function." (PMID 30987032, 2019). "The AM404 + GSK126 was significantly more effective in induction of melanoma cell death compared to the single agents and to PLX4720 and these results were confirmed in 6 additional BRAF-mutant cell lines." (PMID 30710146, 2019). "In fact, the discordant pattern of BRAF and KRAS ctDNA was significantly correlated with the clinical response of melanoma to pembrolizumab treatment and progression of colorectal cancer noted by PET and/or CT scan." (PMID 31727009, 2019). "To this end, we demonstrated that endogenous ITCH interacted with BRAF in both BRAFWT-expressing WM1346 and BRAFV600E-expressing A375 melanoma cells." (PMID 31015455, 2019). "The highest dose level of HCQ (1200 mg daily) correlated with clinical benefit in nine out of 22 patients with refractory B-Raf Proto-Oncogene, Serine/Threonine Kinase (BRAF) wild-type melanoma." (PMID 31569540, 2019).
melanoma (continued). "Combination therapy with BRAF and MEK inhibitors has been shown to reduce the rate of acquired resistance and lead to improved response rates in BRAFV600-mutant advanced melanoma." (PMID 31781977, 2019). "K27-linked ubiquitination of BRAF abolishes 14–3–3-mediated suppression of BRAF kinase activity, leading to sustained BRAF/ΜEK/ERK signaling, which contributes to the pro-tumoral cytokine-facilitated survival of melanoma cells." (PMID 31015455, 2019). "Different BRAF, NRAS, Nf1 and KRAS mutant-driven syngeneic mouse melanoma models have been created and characterized." (PMID 31416487, 2019). "We also selected the A375 (BRAF mutant) and IPC-298 (NRAS mutant) to validate drug combination predictions for these melanoma subtypes, as they represented cell lines where the full matrix of drug combinations was tested." (PMID 30820351, 2019). "Although monotherapy was clinically effective, the combination therapy of BRAF and MEK inhibitors dramatically changed the response rate and survival of melanoma patients." (PMID 30934534, 2019). "Pre-treatment of melanoma cells with AM404 + GSK126 combination led also to a significant increase in melanoma cell death in response to PLX4720 at 72 h in two BRAF-mutant and PLX4720-resistant melanoma cell lines." (PMID 30710146, 2019). "In this study, resistant A375-NRASQ61K (mutant NRAS) and WM983B-BR (wild-type NRAS) melanoma cell lines were used, which harbor BRAFV600E, and exhibit resistance to BRAF inhibitor, Vemurafenib, compared to its parental cells." (PMID 31578454, 2019). "Inhibition of the BRAF oncoprotein by vemurafenib has been shown to be highly effective in BRAFV600E melanoma patients; in contrast, the same treatment has limited effect on BRAFV600E colon cancer patients due to intrinsic resistance against BRAF inhibitors." (PMID 31083627, 2019). "BRAF‐ and MEK‐inhibitor‐resistant melanoma cell lines showed increased expression of PD‐L1, which is inversely correlated with miR‐17‐5p expression." (PMID 30499222, 2019). "We conducted a meta‐analysis to compare chemotherapy in melanoma with combination of BRAF inhibition and MEK inhibition or BRAF inhibition monotherapy." (PMID 31393083, 2019). "The response of YOVAL1.1 to BRAF and MEK inhibition recapitulates that of human BRAFV600E A375 melanoma, demonstrating its suitability over the commonly used B16 syngeneic melanoma model." (PMID 30718660, 2019). "Tumor-associated B cells have even been proposed to promote resistance to BRAF and MEK inhibitors in melanoma through secretion of IGF-1 and clinical trials evaluating therapeutic B cell depletion in this context are underway (NCT01376713)." (PMID 31200747, 2019). "Collectively, our study reveals a pivotal role for ITCH-mediated BRAF ubiquitination in coordinating the signals between cytokines and the MAPK pathway activation in melanoma cells." (PMID 31015455, 2019). "Taken together, these data indicate that resistance to BRAF and MEK inhibitors largely depends on the reactivation of ERK, which restores growth and survival, particularly in the melanoma system." (PMID 31126017, 2019). "In summary, we found elevated levels of CDK11 protein expression in both BRAF- and NRAS-mutant melanoma cell lines compared to benign melanocytes." (PMID 30987032, 2019). "In the last 10 years, MAP kinase pathway–targeted therapies (BRAF and MEK inhibitors) and immune checkpoint inhibitors blocking CTLA-4 and PD-1 have revolutionized the management of advanced melanoma and significantly prolonged patient survival." (PMID 31028434, 2019). "A PI3K/mTOR inhibitor, GSK2126458A, given in combination with dabrafenib efficiently counteracted the stimulating effects of a BRAF inhibitor on invasiveness, and VEGF-A and MMP-9 secretion in A375R melanoma cells resistant to darafenib." (PMID 31295843, 2019). "However, other non-classical BRAF mutations are reported with lower incidence in melanoma samples." (PMID 31547467, 2019).
melanoma (continued). "The combination of BRAF inhibitor and MEK inhibitor was found to be superior with less adverse effects in the treatment of advanced melanoma." (PMID 30886831, 2019). "For example, despite the initial rapid response rates with BRAF and MEK inhibitor combinations in melanoma patients, resistance typically emerges within the first two years of therapy." (PMID 31581557, 2019). "Mutational activation of BRAF is the most prevalent genetic alteration in human melanoma and the CAP and SN co-treatment demonstrated the suppression of oncogenic BRAF during melanoma maintenance." (PMID 31126298, 2019). "We further explored the relationship between the prognostic model and the common BRAF and NRAS mutant in melanoma." (PMID 31649871, 2019). "Although BRAF is stabilized in melanoma cells, polyubiquitination of endogenous BRAF was observed in both BRAFWT- and BRAFV600E-expressing melanoma cells." (PMID 31015455, 2019). "Development of resistance to inhibitors of BRAF (BRAFi) and MEK (MEKi) remains a great challenge for targeted therapy in patients with BRAF-mutant melanoma." (PMID 31227006, 2019). "Association of AM404 and GSK126 induced a strong pro-apoptotic effect even in BRAF/NRAS wild-type cell lines and in NRAS-mutant melanomas, compared to treatment with single agents." (PMID 30710146, 2019). "On the other hand, although BRAF ubiquitination is attenuated in ITCH-depleted, BRAFV600E-expressing 1205Lu melanoma cells, p-MEK and p-ERK levels in 1205Lu cells were not affected." (PMID 31015455, 2019). "To the best of our knowledge, we found for the first time that both BRAF‐ and NRAS‐mutant melanoma cells exposed to magnolol exhibited lower levels of the active histone mark H3K4me3, which presumably will lead to less transcriptional activity." (PMID 30793515, 2019). "In line with this, enforced expression of BRAF(V600E) in melanoma cells has been shown to upregulate the expression of glycolytic and PPP enzymes to sustain melanoma cell growth and proliferation." (PMID 30487597, 2019). "Although the main driver genes (BRAF, NRAS, C-KIT, NF, GNAQ) have been discovered, these markers cannot act as individual indicators for every melanoma case." (PMID 30900145, 2019). "Conversely, the increase of the repressive histone mark, H3K9me3 was consistently observed in BRAF‐ and NRAS‐mutant melanoma cells upon exposure to magnolol and decreased upon activation of Akt." (PMID 30793515, 2019). "Recently developed targeted treatment directed against mutant BRAF and downstream mitogen-activated protein kinase (MAPK) MAP2K1 (also termed MEK1) have improved overall survival of melanoma patients." (PMID 30987166, 2019). "Vemurafenib, an inhibitor that induces apoptosis in cells expressing mutant (V600E) serine/threonine-protein kinase B-raf (BRAF), seen in > 50% of malignant melanomas." (PMID 31727120, 2019). "Alterations of the oncogenes BRAF and NRAS, which act through the MAP-kinase pathway, are the most frequent early events that drive melanocyte proliferation in both nevi and melanoma." (PMID 31861163, 2019). "Interestingly, it was reported that BRAF inhibition could promote the immune response to melanoma." (PMID 31028434, 2019). "In support of a key role for PP2A in regulating BRAF activity, we found that in melanoma cells, depletion of PPP2CA or PPP2R2A led to increased p-S365-BRAF and decreased MEK/ERK activity." (PMID 31015455, 2019).
melanoma (continued). "Furthermore, a study done in melanoma cells showed that BRAF activating mutation was associated with reduced TCA cycle and oxidative phosphorylation and increased glycolysis as a source of energy and BRAF p.V600E inhibitor-resistant cells switch to glutaminolysis to sustain their survival rate." (PMID 31835496, 2019). "Inhibition of BRAF and MEK is standard-of-care targeted therapy for BRAFV600E melanoma, and the clinical response rate of BRAFV600E melanoma to combined BRAF/MEK inhibition is around 70%44." (PMID 30718660, 2019). "Current indications include combination therapy with ipilimumab for BRAF V600 wild-type, unresectable/metastatic melanoma and adjuvant therapy following complete surgical resection for patients with stage III melanoma." (PMID 31640266, 2019). "Another report showed that targeting ERK5 impaired drug resistance to combined inhibition of BRAF and MEK1/2 inhibitors in melanoma." (PMID 30901834, 2019). "Results from our model suggest that melanoma cell lines initially sensitive to vemurafenib have elevated expression of p-MEK and p-BRAF when compared to inherently resistant cell lines." (PMID 31672130, 2019). "Randomized clinical trials reporting on CVAEs in patients with melanoma being treated with BRAF and MEK inhibitors compared with patients with melanoma being treated with BRAF inhibitor monotherapy were selected." (PMID 31397860, 2019). "The treatment with BRAF inhibitor vemurafenib led to an increase of CCL2, which acts as an autocrine growth factor in melanoma." (PMID 30499222, 2019). "Our results coherently demonstrate that ITCH positively regulates the BRAF/MEK/ERK signaling cascade and facilitates the survival of BRAFWT melanoma cells." (PMID 31015455, 2019). "The effects of MAPK suppression on NOXA mRNA were seen in both BRAF and NRAS mutant melanoma cell lines." (PMID 31727958, 2019). "The introduction of BRAF/MEK inhibitors as well as checkpoint inhibitors with anti-CTLA-4 and anti-PD-1 antibodies has offered new hope for patients with stage 4 melanoma." (PMID 30617871, 2019). "PET-16 synergized with BRAF inhibitor PLX4032 and reduced the level of phospho-FAK, impaired migration, invasion and metastasis in cell and animal models of melanoma." (PMID 31652993, 2019). "Recently, new cartridges have been designed to allow the simultaneous detection of the most relevant BRAF and NRAS clinical alterations in a single assay, which is of interest for colorectal tumors and melanoma." (PMID 31415669, 2019). "Based on previous results we decided to focus our attention on two melanoma cell lines, namely WM266 and WM115, which show early and intermediate times of NRG-1 up-regulation upon BRAF inhibition respectively." (PMID 31557826, 2019). "The BRAFV600E mutation occurs in 50–60% of melanomas, and small molecule kinase inhibitors targeting BRAF and MEK have become the standard treatment for patients with inoperable BRAFV600E melanoma." (PMID 30577494, 2018). "Consistently, pharmacological inhibition of SCD1 efficiently targeted melanoma CSCs and attenuated YAP/TAZ activity, partly reverting their resistance to BRAF and MEK inhibitors." (PMID 30558661, 2018). "Mutant BRAF V600E was identified in tumor tissue (fresh biopsy n= 20, FFPE n= 3) in 5% of non-melanoma CoPPO patients (23/455 patients) including colorectal (n=16), bile duct (n=4), lung (Non-Small Cell Lung Cancer, NSCLC) (n=2), and pancreatic cancers (n=1)." (PMID 30220966, 2018). "The suppression of SOX10 in melanoma cells activates TGF-β signaling and can promote resistance to BRAF and MEK inhibitors." (PMID 29315345, 2018). "Since combined BRAF and MEK inhibitor treatment is a standard of care for BRAF-mutant melanoma patients, we further assessed the cell proliferative response to SREBP inhibition in A101D BMR and D10 BMR." (PMID 29950559, 2018).
melanoma (continued). "As FOSL1 (Fra-1) links the BRAF/NRAS pathway to TWIST (see Discussion below), we chose to verify the microarray results from the xenograft experiment in the patients’ melanoma samples by staining for FOSL1." (PMID 30089785, 2018). "Correlation equality tests between WGCNA defined modules in BRAF+/− SU2C cell lines, BRAF+/− TCGA melanoma patients, and BRAFv600e+/− TCGA melanoma patients." (PMID 30042785, 2018). "In the last decade, the treatment with BRAF and MEK kinase inhibitors improved the prognosis of advanced melanoma." (PMID 30154717, 2018). "In conclusion we have shown leflunomide to work in combination both with BRAF and MEK inhibitors in preventing melanoma growth." (PMID 29423085, 2018). "Taken together, these data indicate that SREBP-1 contributes to the anti-tumor response induced by BRAF inhibition and that SREBP-1 inhibition sensitizes therapy-resistant melanoma cells to MAPK-targeting therapy." (PMID 29950559, 2018). "In contrast to dabrafenib, another BRAF inhibitor vemurafenib, which also suppresses proliferation of BRAF-mutated melanoma cells, does not suppress RIP3 activity, indicating that these kinase inhibitors act similarly, but their effect on cancer cells may differ depending on cellular context." (PMID 30237400, 2018). "The parental melanoma cell lines SK-MEL-28 and A375 were exposed toincrementally increasing concentrations of the mutant-BRAF inhibitor vemurafenib." (PMID 29615030, 2018). "Nivolumab, the second PD-1-targeting checkpoint inhibitor approved for melanoma, was compared to investigator choice chemotherapy (ICC) as second- or later-line treatment in patients who were refractory to ipilimumab or BRAF agents." (PMID 29943192, 2018). "Further studies, including a larger series of melanoma patients, are needed to better clarify the impact of MMP-9 as a marker of response to treatment with BRAF inhibitors." (PMID 30154717, 2018). "Hsp90i have been reported to overcome acquired resistance to BRAF and MEK inhibitors in melanoma cell lines." (PMID 29507054, 2018). "Hence, the information about the presence or absence of a certain mutation in BRAF or NRAS or KIT is not sufficient to predict whether or not a melanoma cell will enter the brain." (PMID 30053879, 2018). "An important implication of these observations is the possibility of overcoming resistance to BRAF/MEK-targeting therapies by combining them with BEV and/or other immune therapies in these subgroups, as has been suggested in melanoma." (PMID 29763623, 2018). "In contrast, BRAFV600E/K positive melanoma cells tend to express undetectable or low levels of most RTKs, most likely because the strong endogenous MAPK activation by mutant BRAF selects against active RTK signaling to avoid senescence." (PMID 30237393, 2018). "We also confirmed that the PROG melanomas carrying the AKTQ79K or PIK3CAD350G/E545G mutations both displayed re-activation of MAPK activity, suggesting that PI3K/AKT activation may have contributed to the selection of additional events that conferred robust BRAF/MEK inhibitor resistance." (PMID 30237495, 2018). "The in vitro results showed that NEO412 effectively killed melanoma cells, including TMZ-resistant and BRAF mutant ones, through DNA alkylation and subsequent apoptosis." (PMID 30651933, 2018). "The administration of BRAF inhibitors benefits the OS and RFS of melanoma patients; however, after approximately 6 months of treatment, patients experience fatal drug resistance or the recurrence of metastases." (PMID 30400954, 2018). "Interestingly, melanoma with NRAS mutations virtually never presents BRAF mutations." (PMID 29371600, 2018). "In the vast majority of progressing melanomas, resistance occurs via the re-activation of MAPK signalling, commonly via alterations in BRAF, NRAS and MEK1/2." (PMID 30237495, 2018).